FGFR1 (fibroblast growth factor receptor 1)
Diseases named in the same sentence as FGFR1 in open-access papers (continued):
Sharing a sentence is not in itself a finding about the gene and the disease.
lung carcinoma (continued). "In lung cancer cell lines (H1581 and DMS114), FGF2-dependent activation of the FGFR1/ERKs pathway led to upregulation of SOX2 (Sry-related HMG box 2), which in turn promoted EMT and cell migration." (PMID 34830951, 2021). "Among identified pathways, we highlight the EGFR, FGFR1, KRAS, and PI3K-AKT signaling, and other well-known lung cancer pathways, such as MAPK and mTOR." (PMID 32726984, 2020). "Accordingly, lung cancer cell lines (like NCI-H1581 and NCI-H520 cells) have been identified that harbor amplification of FGFR1 and are highly sensitive to FGFR inhibitors in vitro and in vivo." (PMID 33317057, 2020). "In lung cancer, FGFR1 has been found amplified in about 6% of patients classified either as SCLC or NSCLC, and FGFR1 amplifications are predominant (~17%) in patients with SCC followed by SCLC (~6%) and adenocarcinoma (~1%)." (PMID 33317057, 2020). "The role of a critical oncogene fibroblast growth factor receptor 1 (FGFR1), which was reported as a target of miR-198 in lung cancer, was also investigated." (PMID 31138759, 2019). "It is known that FGFR1 can facilitate tumor development by promoting EMT in various cancers, including lung cancer, gastric cancer, prostate cancer, and breast cancer." (PMID 31492847, 2019). "Here, we presented an EGFRL858R/T790M/FGFR1 dual-inhibitor 15c, which can simultaneous inhibited the kinase activity of EGFRL858R/T790M and FGFR1 both in kinase assay and cell study, for the treatment of FGFR1-amplified EGFR-TKIs resistant lung cancers." (PMID 31998131, 2019). "In terms of the critical roles of the FGFR1-related pathway in NSCLC progression, FGFR1 amplification has been identified in all types of lung carcinoma." (PMID 31815619, 2019). "Accordingly, recent studies have shown that FGFR1 activation promotes EMT and metastasis through different signaling pathways in various tumors as prostate, breast, and lung cancers." (PMID 30866584, 2019). "In lung cancer, YAP1 increases FGFR1 expression, and in cholangiocarcinoma, cross-talk between YAP1 and FGFR1, 2 and 4 has been shown." (PMID 30909436, 2019). "Here, we used the lung cancer cells DMS114, which carry genetic activation of FGFR1, as a cancer cell model to investigate AR to FGFR1-TKIs." (PMID 30140389, 2018). "FGFR1 amplification has been identified in breast cancer, head and neck squamous cell carcinoma, ovarian cancer, ESCC, bladder cancer and lung cancer." (PMID 29179482, 2017). "In this study, we discovered that FGFR1 inhibitor AZD4547 decreased the ALDH-positive population, which was regarded as a stem cell marker in FGFR1-amplified lung cancer cells." (PMID 26936993, 2016). "Considering the lower endogenous expression of FGFR1, FGFR3 and FGFR4 in human lung cancer cell line H441 and H358, we forced expression of full-length FGFR1, FGFR3 and FGFR4 in H441 cells." (PMID 27893433, 2016). "Three of the sensitive lung cancer cell lines, DMS 53, DMS 114, and NCI-H520, harbored FGFR1 amplification and were previously shown to respond to GSK3052230 treatment." (PMID 27223434, 2016). "Intense research is ongoing regarding strategies to target oncogenic FGFR1 and several clinical trials to evaluate the efficacy of various FGFR inhibitors in patients with lung cancer are currently active or have already been completed." (PMID 27367030, 2016). "Nevertheless, despite the initial success of FGFR1-targeting small molecule therapy, occurrence of acquired therapy resistance is one factor limiting the successful application of FGFR inhibitors in lung cancer." (PMID 27367030, 2016). "Silencing FGFR1 by siRNA or FGFR kinase inhibitors can both inhibit the growth of lung cancer cells effectively and block lung cancers in mice." (PMID 24980830, 2014). "Cell models used included Hep3B, C3A, HepG2 and Huh7, several of which showed an upregulation of erlotinib-resistance genes, AXL, HGF, FGFR1 and ERBB3 in comparison to an erlotinib-sensitive lung cancer line." (PMID 24551227, 2014).
lung carcinoma (continued). "HDAC3, one of chidamide’s targets, has been implicated in chemoresistance in various malignancies: it is essential for Kras-mutant lung cancer progression by co-regulating transcription with NKX2-1 and promoting FGFR1 expression, with its inhibition restoring trametinib sensitivity." (PMID 41326348, 2025). "Furthermore, there is evidence that the FGFR1-depending activation of ERK and FAK affects epithelial-mesenchymal transition and leads to tumor growth and distant organ metastasis in lung cancer." (PMID 37445817, 2023). "Furthermore, when we screened 135 lung cancer and 1,182 other cancer cell lines, numerous cells that expressed high FGF2 or FGF9 showed relatively higher expression levels of FGFR1, FGFR2, or both." (PMID 37880373, 2023). "The fibroblast growth factor 8 (FGF8)/FGF receptor 1 (FGFR1)/extracellular signal-regulated kinase 1/2 (ERK1/2) axis functions in the tumorigenesis in various tumors, including lung cancer, and its role involves involved in the invasion, metastasis and progression of non-neoplastic lesions." (PMID 36629518, 2023). "Examination of CD44/PAK1/AKT activation could help to predict response to FGFR1 inhibition, and combination with AKT or PAK1 inhibitors might pave the way toward an effective therapy for FGFR1-dependent lung-cancer patients in cases of resistance to treatment." (PMID 35853934, 2022). "In order to study different mechanisms of resistance to FGFR1 inhibition in lung cancer cells, we compared the two lung cancer cell lines NCI-H1581 and NCI-H520, both of which harbor an FGFR1 gene amplification and a corresponding overexpression of FGFR1 RNA and protein." (PMID 35853934, 2022). "Database from DepMAP also revealed that FGFR1-4EBP1-amplified cells were more sensitive to the FGFR1 inhibitor ponatinib compared to FGFR1-4EBP1-non-amplified cells in both breast and lung cancer cell lines." (PMID 35626002, 2022). "Additionally, FGFR1 was reported to co-stimulate T cells, and targeting of AXL sensitised lung cancer cells to lymphocyte-mediated cytotoxicity." (PMID 35727847, 2022). "Notably, NOP56 silencing also inhibited NRAS-mutant lung cancer H1299 cells, although the effects on EGFR-mutant (EBC-1) or FGFR1-amplified (H520) lung cancer cells were negligible." (PMID 35039048, 2022). "In summary, our in vitro and in vivo data demonstrate that FGFR1 and PLK1 inhibitors constitute a synergistic drug combination and that the FDA‐approved HCQ further enhances cytotoxicity of the treatment in KRAS‐mutant lung cancer." (PMID 34369083, 2021). "It has been reported that BGJ398 effectively inhibits the activation of ERK but not AKT in FGFR1‐amplified lung cancer cell lines." (PMID 34114373, 2021). "FGFR1 induces cell proliferation and metastasis via ERK11/2–SOX2 signaling in lung cancer." (PMID 34455105, 2021). "We noticed that genetic depletion of FGFR1 increased PLK1 activity and PLK1 reduction upregulated FGFR1 in KRAS‐mutant lung and pancreatic cancer cells, suggesting that FGFR1‐ and PLK1‐mediated pathways reciprocate in KRAS‐mutant lung cancer." (PMID 34369083, 2021). "Thus, combined PLK1/FGFR1 inhibition abolishes ROS homeostasis, leading to oxidative stress‐activated JNK/p38/E2F1 signaling and induction of apoptosis in KRAS‐mutant lung cancer cells." (PMID 34369083, 2021). "In the present study, we examined the dynamic responses of lung cancer cells to KRASG12C inhibitors and found that multiple receptor tyrosine kinases (RTKs), including ERBB2, ERBB3, and FGFR1, may contribute to drug tolerance and resistance." (PMID 34858498, 2021). "PKM2 could form complexes with FGFR1 and RACK1 to participate in the occurrence and development of lung cancer." (PMID 33193873, 2020). "A similar cytotoxic effect of peptibodyF2-MMAE was obtained for non-modified, FGFR1-positive NCH-H520 lung cancer cells." (PMID 33076489, 2020).
lung carcinoma (continued). "Other gene targets with genetic alterations in lung cancer include human epidermal growth factor receptor (HER2), Mitogen-activated protein kinase (MEK), Anaplastic lymphoma kinase (ALK), (ROS1) and Fibroblast growth factor receptor 1 (FGFR1)." (PMID 32984047, 2020). "Similarly, the BRAF gene has been found translocated with TRIM4 in lung cancer and TRIM24 in both melanoma and lung cancer and the FGFR1 gene is translocated with TRIM24 in myeloproliferative syndrome." (PMID 32226386, 2020). "We demonstrated the co-expression of FGFR1 and CCND1 in lung cancer." (PMID 32380883, 2020). "Four cell lines, lung cancer PC9 cells (EGFRL858R+ and FGFR1−), lung cancer H520 cells (EGFR− and FGFR1+), lung cancer H1975 cells (EGFRL858R/T790M+ and FGFR1+), and normal lung epithelial cells Beas-2B cells (EGFR+ and FGFR1+), were chosen for the cytotoxic assay." (PMID 31998131, 2019). "This may explain the phenomenon that high expression of FGFR1 and low expression of KLB in lung cancer tissues were detected." (PMID 31695781, 2019). "miR-214-3p was sharply decreased and showed a significantly negative correlation with FGFR1 in lung cancer patients (n = 30)." (PMID 31492847, 2019). "Cancer cells with FGFR1/2/3 gene amplification and wildtype lung cancer cells (except A431) without detectable driving gene alterations were tested in parallel as controls." (PMID 31221965, 2019). "FGFR1 was also highly expressed in NSCLC and promoted tumor formation in lung cancer by interacting with SOX2, Hippo/YAP1 or Hedgehog pathway as our previously work reported 12, 13, 20, while deficiency of KLB did not influence the FGFR1 levels in cultured endothelial cells." (PMID 31695781, 2019). "The inhibitor also accumulated in lysosomes of FGFR1-negative VL-2 lung cancer cells, as well as of the broncho-epithelial cell line BEAS-2B." (PMID 30544798, 2018). "In this study, expression data taken from a broad panel of mesothelioma cells and lung cancer cell lines demonstrated that high levels of FGF2 and/or FGFR1 RNA expression correlated with the antiproliferative effects of two FGF pathway inhibitors that differ in their mechanism of action." (PMID 27223434, 2016). "The elevated expression of additional 8p genes in FGFR1 amplified tumours is consistent with data suggesting that the FGFR1 amplicon in lung cancer is a broad rather than a focal one." (PMID 26905262, 2016). "Despite the small numbers in these rare lung cancer subtypes, SNV calling using the OncoMap database revealed previously undescribed SNV in FGFR1, CDKN2A, RB1, JAK3, and CTNNB1 for the large-cell type, a BRAF mutation for carcinoid, and an AKT1 mutation for adenosquamous carcinoma." (PMID 26076459, 2015). "FGFR1-positive lung cancer cell line is not sensitive to the Fc-MMAE conjugate, excluding that the observed cytotoxicity of peptibodyF4_1-MMAE may be a result of the Fc-receptor mediated internalization." (PMID 34867353, 2021). "Quantitative real-time PCR (qRT-PCR) demonstrated a lower expression of miR-214-3p in the tumor tissues of lung cancer (n = 30) than in non-tumor adjacent tissues (NATs), while immunohistochemistry (IHC) showed a higher FGFR1 level in the tumor tissues of lung cancer than in the NATs." (PMID 31492847, 2019). "Our study demonstrates that FGFR1/MAPK signaling potentially contributes to brachyury activation and suggests that targeting FGFR1/MAPK may represent a useful strategy to suppress brachyury-driven lung cancer progression." (PMID 27893433, 2016).
lung carcinoma (continued). "To determine whether human FGFR1 will be activated in this mouse system we demonstrated, that murine FGFR1 ligands, such as FGF1 and FGF2 can activate human FGFR1 using the human H520 lung cancer cell line that overexpresses FGFR1." (PMID 27391347, 2016). "Moreover no significant prognostic impact of FGFR1 was found in 8 lung cancer studies (62.2%, 1978/3178)." (PMID 26788508, 2015). "Among them, SCCs are often characterized by FGFR1 amplifications that make these lung tumors dependent on FGF ligands in vitro and in vivo, suggesting FGF blockade by FGF trapping or FGFR inhibition by TK inhibitors might represent promising therapeutic strategies for lung cancer treatment." (PMID 33317057, 2020). "Compared with control human lung cancer cell lines PC‐9 and A925L, KM12SM and HCC78 cells expressed lower levels of EGFR and no detectable levels of FGFR1." (PMID 36416133, 2023). "A previous study reported that FGFR1 mRNA and protein expression, not gene copy number, predicted FGFR TKI sensitivity across all lung cancer histology." (PMID 32596330, 2020). "Squamous lung cancer cells NCI-H520 (FGFR1 positive) internalized about two times more FGF2 and FGF2 dual warhead conjugate than control, FGFR1 negative HCC-15 cells." (PMID 30029518, 2018). "Of these fusions, 16 (including ALK, ARAF, BRAF, FGFR1, FGFR3, RET, and ROS1) and 21 (including ABL1, GNAS, JAK2, and NRG1) were classified as either related to lung cancer, or as oncogenes that have not been reported in lung cancer, respectively." (PMID 36153311, 2022). "However, basic research showed that FGFR1 mRNA and protein expression, not gene copy number, predict FGFR TKI sensitivity across all histopathological lung cancer." (PMID 32626515, 2020). "Subsequently, it was found that a symmetrically structured NDGA derivative of Af23 could effectively inhibit FGFR1 kinase in a non-ATP competitive manner (IC50 = 1.4 μM) and had potent anti-cancer activity against human lung cancer in vitro and in vivo." (PMID 33041789, 2020).
glioma (108 papers, 2006 to 2025). A benign or malignant brain and spinal cord tumor that arises from glial cells (astrocytes, oligodendrocytes, ependymal cells). "Co-occuring hereditary and secondary FGFR1 mutations show unexpected synergies in gliomas, modulating protein stability, signaling and oncogenic transcriptional programs." (PMID 41174249, 2025). "In this study, we report two cases of high-grade glioma with FGFR1 mutation, each characterized by additional massive chromosomal loss." (PMID 41323387, 2025). "In this study, we present two cases of high-grade glioma characterized by a single activating mutation of FGFR1 and massive chromosome loss (near-haploid genome)." (PMID 41323387, 2025). "This study reports synergies of FGFR1 hotspot mutations and secondary cis variants in gliomas, modulating protein stability, signaling interactomes and tumorigenesis-associated transcriptional programs." (PMID 41174249, 2025). "Together, there is an apparent clinical association of OTUD4-CDK1/FGFR1 in the human glioma development." (PMID 38429268, 2024). "Studies have shown that Infigratinib is effective in treating FGFR1-amplified squamous non-small cell lung cancer (sqNSCLC), gliomas with FGFR1 mutations, and urothelial carcinoma with FGFR1 overexpression." (PMID 39590377, 2024). "The receptor tyrosine kinase fibroblast growth factor receptor 1 (FGFR1), undergoes fusion or mutates in a subset of thalamic H3.3K27M gliomas." (PMID 38525424, 2024). "Preliminary evidence shows that single-agent FGFR inhibitors in recurrent gliomas with FGFR1 mutations can achieve durable response." (PMID 39335555, 2024). "Fibroblast growth factor receptor 1 (FGFR1) mutations have been associated with poorer prognoses in pediatric central nervous system tumor patients." (PMID 38903142, 2024). "FGFR inhibitors showed promising efficacy in recurrent gliomas harboring FGFR1 or FGFR3 point mutations or FGFR3-TACC3 fusions." (PMID 36998447, 2023). "As BRAF and FGFR1 mutations are typical hallmarks of low-grade gliomas/glioneuronal tumours such as ganglioglioma or pilocytic astrocytoma, the co-occurrence of H3-K27 and these MAPK alterations makes diagnosis and grading difficult." (PMID 38066305, 2023). "The mutation rate of FGFR1 p.N546K or p.K656E in low‐grade gliomas and mixed neuronal‐glial tumors is 6%, which is the fifth most common gene alteration in these tumors." (PMID 37750089, 2023). "cIMPACT-NOW reported that FGFR1 mutations are typical of low-grade gliomas which indicated an inert clinical behavior and long survival time." (PMID 35432538, 2022). "A recent study associated FGFR1 mutations in low-grade glioma with increased risk for intracranial bleeding." (PMID 35018490, 2022). "Another integrated molecular analysis of 70 low-grade glioma cases with NF1 tumors revealed 3 FGFR1 hotspot mutation." (PMID 35018490, 2022). "FGFR1 expression has been associated with the increased motility of multiple cancers, for example colorectal and lung cancers, as well as gliomas cells." (PMID 33637089, 2021). "Similar to FGFR1 WT cases, cases with additional FGFR1 mutation displayed features of a diffusely growing glioma with increased cellularity and signs of anaplasia, such as increased cell pleomorphism, mitoses, or vessel proliferation." (PMID 33433639, 2021). "Oncogenic mutations of the FGFR1 tyrosine kinase domain (N546K and K656E) were frequently discovered in glioma." (PMID 34272467, 2021). "FGFR1 expression is positively associated with more invasive and malignant adult gliomas and thus positively associated with poorer prognoses." (PMID 30931252, 2019). "Following recent reports of recurrent FGFR1 mutations in pediatric gliomas and known roles for FGFR1 in invasion in other cancer types, we firstly wanted to determine clinical relevance of FGFR1 expression." (PMID 30931252, 2019). "Recently, recurrent Fibroblast growth factor receptor 1 (FGFR1) mutations in pediatric gliomas have been reported." (PMID 30931252, 2019).